MIR7856 (microRNA 7856)
Synonyms: hsa-mir-7856
Gene: MicroRNA gene on chromosome 1 (86,357,632 to 86,357,687, reverse strand). Ensembl gene ENSG00000278281.
Homologues: Orthologues: chimpanzee MIR7856 (100% identical).